IL6 (interleukin 6)
Diseases named in the same sentence as IL6 in open-access papers (continued):
Sharing a sentence is not in itself a finding about the gene and the disease.
Anxiety (continued). "More recently, depletion of Treg cells in wild-type mice potentiated depressive-like and anxiety-like behaviours, as well as serum IL-6 and TNF levels following chronic restraint." (PMID 25986444, 2015). "In a mouse model of ovarian cancer, increased levels of interleukin-6 (IL-6) were shown to partially mediate anxiety-like behaviours." (PMID 26569330, 2015). "Influence of the vagal tone on the plasma levels of the morning salivary and plasma cortisol, IL-6, norepinephrine concentrations, state-anxiety and depressive symptomatology scores in Controls, Crohn’s disease (CD) and Irritable Bowel syndrome (IBS) patients." (PMID 25207649, 2014). "The low-grade levels of the systemic inflammatory mediators IL-6, IL-12p70 and IL-17A correlated to memory, anxiety, anhedonia and species-typical behavior, indicating a possible influence on behavior." (PMID 25133574, 2014). "Thirdly, mice with elevated IL-6 in the brain display many autistic features, including impaired cognitive abilities, deficits in learning, abnormal anxiety traits and habituations, as well as decreased social interactions." (PMID 25407263, 2014). "The students who received omega-3 supplementation showed a 14% reduction in lipopolysaccharide stimulated interleukin 6 (IL-6) and 20% reduction in anxiety symptoms measured on the BAI." (PMID 22969831, 2012). "Consistent clinical data report a significant correlation between elevated circulating levels of inflammatory markers, particularly IL-6, and development of anxiety symptoms, including in obese patients." (PMID 21949705, 2011). "Elevated IL-6 and TNF-α levels are frequently associated with depressive and anxiety symptoms." (PMID 41302239, 2025). "Additionally, we found significant positive correlations between IL-8 levels and both anxiety and functional disability, as well as between IL-6 and BMI." (PMID 40507523, 2025). "For example, elevated PFC's pro-inflammatory cytokines (NF-κB and IL-6) may contribute to anxiety-like behavior following repeated morphine administration (10 mg/kg for BID for eight days)." (PMID 41404029, 2025). "In addition, commonly used psychiatric drugs (including anti-depressants, anticonvulsants, and anti-anxiety drugs that were taken by several of the patients in the OA cohort) have been shown to reduce key inflammatory cytokines such as IL-6 and TNF-α." (PMID 40565171, 2025). "Maternal anxiety and alcohol exposure reduce microbial diversity and beneficial Bifidobacterium, potentially affecting neurodevelopment through IL-6/IL-10 pathways." (PMID 41450934, 2025). "Improves state anxiety and functional capacity; decreases IL-6." (PMID 41008984, 2025). "It validated that WDD may inhibit the increase of anxiety behaviors and the proportion of interleukin-6 (IL-6) -positive lymphocytes in mice and reverse the PI3K/AKT signaling pathway and MAPK signaling pathway." (PMID 41356482, 2025). "Notably, systemic inhibition of IL-6 signaling using the MP5 antibody alleviated anxiety-like behaviors, including self-grooming, and deficits in social interaction, highlighting an important role of IL-6 in these behavioral alterations." (PMID 41150800, 2025). "The parameters of interest were IL-6 levels, anxiety, and disability related to MS." (PMID 38921006, 2024). "DHA and EPA may suppress the release of inflammatory cytokines, including TNF-α, Interleukin 1 (IL-1), IL-2, and IL-6, which may have an anti-anxiety or anti-depressive effect." (PMID 38979505, 2024). "Elevated levels of TNF-α and IL-6 may inhibit the synthesis and release of neurotransmitters such as serotonin and dopamine, thereby leading to mood dysregulation disorders like anxiety." (PMID 39295596, 2024). "Interestingly, a correlation was found between anxiety and IL-6 levels and how the psycho-physical process induces the recruitment of monocytes related to IL-6 levels." (PMID 38921006, 2024).
Anxiety (continued). "Interestingly, high levels of IL-6 and TNF-α in the brain have been associated with anxiety behavior in rodents." (PMID 39720795, 2024). "Some studies have found that serum IL-6 level may be related to anxiety symptoms in other diseases, and the use of IL-6 antagonist can significantly improve these anxiety symptoms." (PMID 39295596, 2024). "These factors included age (p = 0.040), Mini-Mental State Examination score (p < 0.001), State-anxiety inventory score (p = 0.014), Trait-anxiety inventory score (p = 0.003), anesthesia time (p = 0.006), hospitalization time (p < 0.001), and IL-6 concentration at T3 (p = 0.003)." (PMID 38590312, 2024). "Further, although we focused on anxiety and frustration, a possibility remains that CSF IL‐6 levels may be related with other psychopathological components, which requires further investigations." (PMID 39317977, 2024). "TNF-α and IL-6 may contribute to the onset of anxiety symptoms in MSA patients through these mechanisms." (PMID 39295596, 2024). "In addition, eight patients above the CSF IL‐6 cut‐off levels also had higher scores of trait anxiety and autonomy frustration than the rest of the patients, and their rCBFs were increased in the NAc, left temporal gyrus, and cerebellum." (PMID 39317977, 2024). "In addition, IL-6 levels are also correlated with the adiposity levels and the degree of anxiety of the subject." (PMID 38921006, 2024). "HPA axis stimulation via IL-6 contributes to stress and anxiety following TBI." (PMID 38840141, 2024). "CCI + sgp130-Fc mice also had decreased peripheral zone time versus CCI + VEH mice, indicating that IL-6 trans-signaling inhibition may influence injury-induced anxiety-like behaviors." (PMID 38840141, 2024). "Downstream effects of IL6 overexpression may account for the decreased anxiety-like phenotype observed." (PMID 38075266, 2023). "The results showed improvement in anxiety and functional capacity along with a decrease in IL-6." (PMID 37229273, 2023). "Depressive-like behavior and anxiety are strongly connected with elevated IL-6 levels." (PMID 37623226, 2023). "Rats with high anxiety-like behavior had elevated IL-6 and IL-10 mPFC levels." (PMID 37064304, 2023). "Interestingly, the decrease in anxiety-like behavior in the EPM was also observed in 1 month old mice where IL6 was overexpressed via an adenovirus injected intraventricularly at birth." (PMID 38075266, 2023). "In addition, molecular docking results indicated that beta-sitosterol and Fumarine were the crucial bioactive components, and AKT1 and IL6 were potential target genes for treating the same pathogenesis of anxiety and PTSD by KXS." (PMID 37986356, 2023). "Additionally, the intervention of CLM + SSRI significantly improved the symptoms of anxiety and insomnia, and reduced serum IL-6 and TNF-α levels." (PMID 37808199, 2023). "Interestingly, greater changes in IL-6 after LPS administration in humans significantly and independently predicted a more pronounced LPS-induced anxiety response." (PMID 36757901, 2023). "Interestingly, TNF-α on D1 and D3, IL-6 on D3, IL-8 on D3 and D7, and IL-17A on D1, D3, and D7 correlated with higher anxiety rate (all P<0.05)." (PMID 37878890, 2023). "In mouse models, it has been associated with increased levels of IL-6, TNF-α, and IFN-γ, a decrease in serotonin and dopamine levels within the hippocampus, induced loss of muscle strength and equilibrium, and increased anxiety and hopelessness." (PMID 38004391, 2023). "We specifically hypothesized that disrupted IL-6 secretion would be associated with perturbed amygdala emotional reactivity and greater depressive/anxiety symptoms; and that it would be predicted by the interactions between psychosocial stressors and IL6/IL6R." (PMID 37324818, 2023). "Because of reduced amygdala volumes, maternal IL-6 levels can predict offspring anxiety." (PMID 37273529, 2023).
Anxiety (continued). "We found that IL‐1β, IL‐6, and zo‐1 mRNA levels in the hippocampus positively correlated with anxiety‐like behavior, while ocln and cldn‐8 mRNA levels negatively correlated with anxiety‐like behavior." (PMID 36650644, 2023). "This action enhances anxiety-like behavior and elevates the expression level of IL-6 in the blood." (PMID 37692303, 2023). "Increased IL-6 levels activate the bone marrow-derived peripheral monocytes and promote their recruitment to neurovascular endothelial cells, thereby releasing IL-1β and triggering anxiety." (PMID 37273529, 2023). "Mice challenged intraperitoneally with S. aureus showed increase of anxiety‐like behaviors, which may be mediated by the overexpression of IL‐6 and TNF‐α in prefrontal cortex and hippocampus." (PMID 35977050, 2022). "Notably, the correlations of TNF‐α and IL‐1β with anxiety seemed to be stronger than IL‐6 and IL‐17." (PMID 34697903, 2022). "A meta-analysis investigating the relationship between anxiety and immune features based on 41 studies found significant differences in pro-inflammatory cytokines, including interleukin-1ꞵ, IL-6, and tumor necrosis factor-α, between healthy controls and people with anxiety disorders." (PMID 35682203, 2022). "IL-6 at age 9 did not mediate the associations between persistent anxiety and any of the psychotic outcomes." (PMID 35151465, 2022). "Therefore, we postulate that HET improves LPS-induced anxiety-like behavior by modulating serum IL-6 levels at an early stage of inflammation." (PMID 36034871, 2022). "Some studies demonstrated that brain IL-6 could mediate autism-like behaviors including heightened anxiety and deficits." (PMID 36082034, 2022). "Because the anxiety-like (EPM test) and depressive-like (TST/FST) behaviors were not significantly modified when 5-FU was administered, we propose that 5-FU evoked symptoms of neurofatigue associated, at least in part, with IL-6." (PMID 36139563, 2022). "Under this condition, microglia are overactivated via the Toll-like receptor 4/nuclear factor-κB signalling pathway, and the levels of interleukin-1β, interleukin-6 and tumour necrosis factor-α significantly increase, inducing depressive and anxiety-like behaviours." (PMID 36209126, 2022). "Although there is no information available to substantiate this presumption, its likeliness is supported by reports showing a correlation between IL-6 (a proinflammatory cytokine) serum concentrations and the appearance of anxiety and depression in infected patients." (PMID 34576830, 2021). "When IL-6 is elevated in the brain of mice they display impaired cognitive abilities, deficits in learning, abnormal anxiety traits and habituations, and decreased social interactions concomitantly with significant disruption of synaptic transmission and structural plasticity." (PMID 33732142, 2021). "The FMT form HV also alleviated the IBD/D−-F-induced anxiety-like behavior, IL-6 expression in the hippocampus, corticosterone, LPS, and IL-6 levels in the blood, and colon shortening, myeloperoxidase activity, and IL-6 expression in the colon." (PMID 34650107, 2021). "In addition, we found a correlation of IL-6-positive cells in the whole hippocampus and anxiety behavior." (PMID 33683478, 2021). "Furthermore, the effects on inflammation parameter (IL-6), stress, anxiety, depressive symptoms, quality of life, and fatigue, as well as the safety of the interventions, were assessed." (PMID 34439234, 2021). "Indeed, an increased number of IL-6-positive cells in the whole hippocampus was connected to an elevated anxiety behavior indicated through more buried marbles (r = 0.461, p = 0.023)." (PMID 33683478, 2021). "Conversely, elevated IL-6 in the CNS results in neuro-impairment through reduced synaptic plasticity in the hippocampus, while ablation of IL-6 in glial cells reduces exploratory behavior and decreases anxiety." (PMID 33921854, 2021).
Anxiety (continued). "Therefore, the aim of this study was to assess the impact of coconut oil and EGCG on the levels of IL-6, anxiety and functional disability in patients with MS." (PMID 31979305, 2020). "For healthy controls, there was a trend toward an association of anxiety (but not depressive symptoms) with stimulated IL‐6 (β = 0.004, P = 0.052)." (PMID 31199593, 2020). "In particular, as anxiety is associated with an increased production of pro-inflammatory cytokines, including tumor necrosis factor-alpha (TNF-α) and interleukin-6 (IL-6), the effect of n-3 PUFAs of decreasing inflammatory cytokines indirectly promote the reduction of anxious symptoms." (PMID 32839416, 2020). "However, QUER has shown the potential to improve abnormalities, such as anxiety-like behaviors, and neuroinflammation by continuously reducing the levels of IL-6 and IL-1β induced by LPS." (PMID 32419805, 2020). "Therefore, the aim of this study was to assess the impact of coconut oil and EGCG on the levels of IL-6 and anxiety related to functional disability in MS patients." (PMID 31979305, 2020). "Nonetheless, patients with a higher concentration of IL-6 in serum show higher levels of anxiety." (PMID 31979305, 2020). "Regarding the intervention group, a significant decrease in serum concentration was produced for IL-6: patients’ anxiety for this group also varied after the diet, significantly decreasing state anxiety, and a significant improvement is shown in functional capacity." (PMID 31979305, 2020). "Inflammatory signalling, such as increased brain-cortical TNF levels in conjunction with either increased IL-6 or IL-1β, and alterations in growth factor levels, e.g. brain derived neurotrophic factor and neuregulin, can contribute to the development of anxiety in eCM and behavioural sequelae." (PMID 32703204, 2020). "However, CVE attenuated the expression of pro-inflammatory cytokines TNF-α and IL-6 and was generally effective at enhancing motor function and reducing anxiety-like behavior in Tg-SwDI mice, though alterations in learning and memory tasks were varied." (PMID 31296239, 2019). "Other recent studies report that diets high in sugars, processed foods (i.e., meat products), and/or fats are related with higher anxiety levels through alterations of glucose, protein and energy homeostasis, and increases in inflammatory cytokines (i.e., IL-6, IL-1β, TNFα) and corticosterone." (PMID 31159322, 2019). "Another explanation for the relationship between elevated IL-6 and fatigue may be related to the anxiety in cancer patients." (PMID 31010015, 2019). "On the other hand, the anxiety state and the IL-6 levels significantly increased throughout the AE." (PMID 29445205, 2018). "Linear regression analysis was used to determine whether the temporal variation across AE of the anger and anxiety state score could be explained by the temporal variation of IL-1β and IL-6 levels in plasma and saliva ascertained at the same time." (PMID 29445205, 2018). "When IL-6 was overexpressed, neural circuit imbalances and abnormalities in synaptic plasticity were evident, followed by impaired cognition, learning deficits, abnormal anxiety-related behavior, and reduced social interactions." (PMID 29447237, 2018). "Peripheral administration of LPS induces inflammatory cytokines such as tumor necrosis factor (TNF) α, interleukin (IL)-1β, IL-6 which may produce depressive or anxiety-like behavior." (PMID 29228944, 2017). "In our study, NNAV showed a potential to reduce the anxiety-like behavior, and these may be due to the inhibitory effect on the secretion of IL-6 and TNF-α." (PMID 25093033, 2014). "Similarly, higher scores on the Spielberger State-Trait Anxiety Inventory were significantly correlated with elevated C-reactive protein, interleukin-6 and fibrinogen levels in 853 middle-aged adults." (PMID 22808180, 2012).
Anxiety (continued). "Correlation analyses revealed strong associations between the increases in anxiety and negative mood and circulating IL-6 levels in the high-dose and concentrations of cortisol in the low-dose LPS group." (PMID 22164271, 2011). "Likewise, experimental studies using IL-6-deficient mice or rats bred for extremes in anxiety-related behavior support a role of IL-6 in anxiety-like behavior." (PMID 21949705, 2011). "Furthermore, we suggest that pro-inflammatory cytokines such as TNF-α and IL-6-key indicators of stress-induced inflammation-may serve as predictors of anxiety-related vulnerability." (PMID 41853172, 2026). "Notably, HSP resulted in a significant attenuation of anxiety- and depression-associated behaviors, a reduction in pro-inflammatory cytokine levels (TNF-α, IFN-γ, IL-1β, IL-2, IL-6), and an augmentation of neurotrophic factors (NT-3, BDNF, NGF) within the striatum." (PMID 41346684, 2025). "Notably, IL-6 was particularly associated with aspects of well-being related to physical discomfort and fatigue, rather than cognitive or anxiety-related symptoms." (PMID 40806940, 2025). "Oxidative stress, high levels of cytokines (TNF-α, IL-1β, IL-6, IL-10), and dysregulation of the proliferation and differentiation of oligodendrocytes and astrocytes were observed in the prefrontal cortex and hippocampus of T1D mice exhibiting concomitantly anxiety-like behavior." (PMID 38279738, 2024). "However, significant reductions in interleukin-6 and state anxiety levels were observed, indicating that the combination could have anti-inflammatory and anxiolytic benefits." (PMID 39203859, 2024). "Among children with tic disorders, state anxiety scores were significantly and positively correlated with IL-17 levels (rho = 0.32, p = 0.006), whereas among control children, state anxiety correlated significantly and negatively with IL-6 levels (rho =− 0.25, p = 0.026)." (PMID 38956051, 2024). "However, those reporting myalgia, low mood, and anxiety at follow‐up had lower admission levels of IL‐6 (34.9 vs. 52.0 pg/mL, p = .043), CRP (83 vs. 105 mg/L, p = .048), and ferritin (357 vs. 568 ug/L, p = .01) respectively, compared with those who did not report these symptoms." (PMID 37904690, 2023). "Moreover, while the IL-6 diurnal index was associated with depressive symptoms, the total IL-6 output did not correlate with anxiety or depressive symptoms." (PMID 37324818, 2023). "At the end of the 12-week experiment, anxiety-like behavior was evaluated by the light/dark box test; compulsive-like behavior by Marble burying, transcriptional regulation of genes Lrrk2, Tlr4, Nfat, Drd1, Drd2, Il6, Il1β, Il10, and iNOS by RT-qPCR; and inflammatory markers by flow cytometry." (PMID 37063320, 2023). "Furthermore, evidence showed that anxiety could enhance the production of proinflammatory cytokines, including interleukin-6 which has been proven as a promising marker for delirium." (PMID 36997928, 2023). "Moreover, bergamot essential oil could relieve anxiety-like behaviors of aluminum trichloride-exposed rats via downregulating the levels of IL-1β, IL-6 and TNF-α in the hippocampus and the frontal cortex." (PMID 36358502, 2022). "In addition, clinical and basic studies have proven that microglial activation as well as proinflammatory cytokines, such as TNF‐α and IL‐6, arising from both peripheral and CNS induced by infection or stress response was involved in the development of anxiety‐like behaviors." (PMID 35977050, 2022). "MR analyses provided consistent results suggesting that genetically predicted higher IL-6 activity was associated with increased risk for depressive symptoms, while genetically-predicted higher CRP concentration was associated with decreased risks of depressive and anxiety symptoms." (PMID 34505025, 2021).